ME1 (malic enzyme 1)
Diseases named in the same sentence as ME1 in open-access papers (continued):
Sharing a sentence is not in itself a finding about the gene and the disease.
skin cutaneous melanoma (2 papers, 2022 to 2025). "ME1 exhibited a positive correlation with immune infiltration in several tumor types, including GBM, sarcoma (SARC), kidney renal papillary cell carcinoma (KIPAN), PRAD, skin cutaneous melanoma (SKCM), BLCA, LAML, and OV." (PMID 40510340, 2025). "We analyzed data from the skin cutaneous melanoma cohort and could identify significant negative correlation between the NRF2 target malic enzyme 1 (ME1) and KIT as well as ABCB5." (PMID 34951143, 2022).
synovial sarcoma (2 papers, 2023 to 2025). "Notably, ME1‐deficient synovial sarcoma cells were also found to have intercellular iron accumulation." (PMID 36840630, 2023).
triple-negative breast carcinoma (2 papers, 2018 to 2024). An invasive breast carcinoma which is negative for expression of estrogen receptor (ER), progesterone receptor (PR), and human epidermal growth factor receptor 2 (HER2). "Stratification analysis indicated ME1 upregulation was significantly associated with poor DSS (p = 0.039) and DFS (p = 0.038) in patients with non-triple-negative breast cancer (TNBC)." (PMID 38445776, 2024).
chronic obstructive pulmonary disease (1 paper, 2024). A chronic and progressive lung disorder characterized by the loss of elasticity of the bronchial tree and the air sacs, destruction of the air sacs wall, thickening of the bronchial wall, and mucous accumulation in the bronchial tree. "Reduced ME1 expression in alveolar macrophages (AM) and peripheral blood monocyte-derived macrophages (MDM) from patients with chronic obstructive pulmonary disease (COPD) has been linked to defects in the phagocytosis process of bacteria such as Haemophilus influenzae and Streptococcus pneumoniae." (PMID 39763664, 2024).
Cirrhosis (1 paper, 2023). A chronic disorder of the liver in which liver tissue becomes scarred and is partially replaced by regenerative nodules and fibrotic tissue resulting in loss of liver function. "A total of 97 HCC patients with cirrhosis were selected from TCGA, and 5 genes (ADH1C, ACSL4, GPD2, ME1, NCAPH2) were selected to construct a FAM-related prognosis signature via Lasso–Cox regression using this cohort." (PMID 36671526, 2023).
colorectal adenocarcinoma (1 paper, 2018). The most common type of colorectal carcinoma. "Robust expression of ME1 was observed in the more differentiated epithelial regions of both human colorectal adenocarcinomas and normal colon." (PMID 30250042, 2018).
colorectal tumors (1 paper, 2022). "We cannot rule out that additional mutated genes, such as KRAS, could interact with the ME1 function, since mutations in the latter were shown to increase ME1 mRNA levels in colorectal tumors." (PMID 36612292, 2022).
COVID-19 (1 paper, 2023). A disease caused by infection with severe acute respiratory syndrome coronavirus 2. "The use of me1 Ψ was also utilized in the COVID-19 mRNA vaccines developed by both Pfizer-BioNTech and Moderna, which were the first approved mRNA therapeutics." (PMID 37650117, 2023).
hyperlipidemia (1 paper, 2022). "As for the negatively correlated proteins (Fabp2, Slc27a4, Me1), they are mainly involved in lipid uptake and lipid biosynthesis, which indicates hyperlipidemia might inhibit the formation of HDL-c." (PMID 36234935, 2022).
hyperphosphatemia (1 paper, 2017). Abnormally high level of phosphate in the blood. "In contrast, a single injection of ME‐1 resulted in hyperphosphatemia and a significant reduction in Pi excretion 2 days after treatment, while no changes in serum Mg2+ or Mg2+ excretion were observed." (PMID 28292888, 2017). "Interestingly, a single dose of ME‐1 was effective in reducing Pi excretion and triggering hyperphosphatemia." (PMID 28292888, 2017).
hyperthyroidism (1 paper, 2016). Overactivity of the thyroid gland resulting in overproduction of thyroid hormone and increased metabolic rate. "Thus, a higher expression of TH-responsive genes Dio1 and Me1 was noted in hyperthyroidism in female mice liver, and Tbg transcripts were elevated in hypothyroid female liver compared to male mice." (PMID 27559466, 2016).
Hypomagnesemia (1 paper, 2017). An abnormally decreased magnesium concentration in the blood. "Here, we inject mice with the anti‐EGFR monoclonal antibody ME‐1 for 2 weeks and observe a significant increase in serum Pi and mild hypomagnesemia, but no changes in Pi or Mg2+ excretion." (PMID 28292888, 2017).
intestinal cancer (1 paper, 2018). "Collective results implicate ME1 as a functional contributor to intestinal cancer development and suggest that targeting ME1 should be explored as a potential therapeutic strategy to improve patient outcome." (PMID 30250042, 2018).
ischemia (1 paper, 2023). A hypoperfusion of the BLOOD through an organ or tissue caused by a PATHOLOGIC CONSTRICTION or obstruction of its BLOOD VESSELS, or an absence of BLOOD CIRCULATION. "Hepatic ischemia/reperfusion (I/R) results in down‐regulation of Malic enzyme 1 (Me1), which is known to replenish the intracellular reducing equivalent and to maintain redox homeostasis." (PMID 36840630, 2023).
leukemia (1 paper, 2022). A malignant (clonal) hematologic disorder, involving hematopoietic stem cells and characterized by the presence of primitive or atypical myeloid or lymphoid cells in the bone marrow and the blood. "Our results showed that the knock-down of ME1 reduced the proliferative capacity of AML cell lines, demonstrating the impact of ME1 on key processes contributing to leukemia progression." (PMID 36612292, 2022).
lupus erythematosus (1 paper, 2024). An autoimmune, connective tissue chronic inflammatory disorder affecting the skin, joints, kidneys, lungs, heart, and the peripheral blood cells. "Our in silico analysis unveils a significant upregulation of ME1 gene expression in rheumatoid arthritis and lupus erythematosus highlighting a potential role of ME1 in inflammatory diseases." (PMID 39335602, 2024).
lymph node metastasis (1 paper, 2020). "However, a significant correlation was observed only with ME1 with respect to grade and only with budding in the presence of lymph node metastasis." (PMID 32998265, 2020).
melanoma (1 paper, 2022). A malignant, usually aggressive tumor composed of atypical, neoplastic melanocytes. "ME1, which localizes to the cytoplasm, was expressed by most melanomas but it tended to higher in G6PD mutant as compared to control melanomas." (PMID 35110412, 2022).
metabolic dysfunction-associated steatohepatitis (1 paper, 2024). Metabolic dysfunction-associated steatohepatitis (MASH, formerly known as nonalcoholic steatohepatitis or NASH) is a type of fatty liver disease. "Furthermore, both ACLY and ME1 are found upregulated in PBMC-derived macrophages from metabolic dysfunction-associated steatohepatitis (MASH) patients." (PMID 39335602, 2024).
osteosarcoma (1 paper, 2022). A usually aggressive malignant bone-forming mesenchymal neoplasm, predominantly affecting adolescents and young adults. "In human osteosarcoma U2OS cells and normal diploid fibroblast IMR90 cells, the forced expression of ME1 or ME2, or the addition of a malic enzyme substrate, increased the cellular NADPH levels." (PMID 36612292, 2022).
pancreatic adenocarcinoma (1 paper, 2025). "In cancer, particularly in KRAS-dependent pancreatic adenocarcinoma, the Glutamate Oxaloacetate Transaminase 1 (GOT1)-MDH1-ME1 axis is reprogrammed to enhance NADPH production; silencing GOT1 or suppressing ME1 leads to intracellular ROS accumulation, redox imbalance, and loss of proliferation." (PMID 41142618, 2025).
schwannoma (1 paper, 2024). A benign, usually encapsulated slow growing tumor composed of Schwann cells. "Next, we tested whether reduced levels of AKR1, 2, 3, and ME1 can also be observed in primary schwannomas from patients." (PMID 38879607, 2024).
Sepsis (1 paper, 2025). Sepsis is defined as life-threatening organ dysfunction caused by a dysregulated host response to infection. "For instance, gene module ME1 was downregulated, while ME2, ME3 and ME4 were upregulated in sepsis samples compared to healthy controls." (PMID 40965975, 2025).
small intestine adenoma (1 paper, 2018). "This study reports a novel in vivo association between gastrointestinal ME1 expression and small intestine adenoma burden." (PMID 30250042, 2018).
type 2 diabetes mellitus (1 paper, 2023). A type of diabetes mellitus that is characterized by insulin resistance or desensitization and increased blood glucose levels. "Earlier studies have associated ME1 gene/protein as a possible contributor to type 2 diabetes susceptibility in humans and with lipogenesis and adiposity in domestic animals." (PMID 37047583, 2023).
wasting syndrome (1 paper, 2014). "Taken in conjunction with levels of Me1 and Pdk1, it appears that AHR-less-active animals may preferentially utilize nitrogenous molecules as sources of energy and that this preference may somehow confer a protective effect against TCDD-induced wasting syndrome." (PMID 25467400, 2014).
cancer (53 papers, 2012 to 2025). A tumor composed of atypical neoplastic, often pleomorphic cells that invade other tissues. "Firstly, We reviewed the existing literature and found that ME1, a key metabolic gene, is associated with various cancers." (PMID 40510340, 2025). "The cancer-specific nature of these associations indicates complex, context-dependent interactions between ME1 and the tumor immune microenvironment." (PMID 40510340, 2025). "Given the significant role of gene mutations in tumor development, we utilized the CBioPortal platform to conduct a comprehensive analysis of ME1 mutations across various pan-cancers." (PMID 40510340, 2025). "In this study, we conducted a comprehensive bioinformatics analysis of ME1 across various cancer types, focusing on its expression levels, mutations, methylation levels, immune infiltration, and potential functional roles." (PMID 40510340, 2025). "Similar to loss of PC, loss of ME1 had minimal effect on cancer cell proliferation in monoculture, but reduced growth of organoid co-cultures compared to controls." (PMID 32648540, 2020). "It has been previously shown that Nrf2 can redirect glucose and glutamine to anabolic pathways in cancer cells, and Me-1 is implicated in these pathways; however, these results in cancer cells cannot necessarily be safely extrapolated to nontransformed hepatocytes." (PMID 23710285, 2013). "ME1 may induce hyperinsulinemia, hyperglycemia, inflammation, and oxidative stress in patients with obesity and type 2 diabetes and is a risk factor for the development of malignant tumors in these diseases." (PMID 39996805, 2025). "Our pan-cancer analysis revealed that ME1 expression varies across different tumor types, and this heterogeneity reflects its context-dependent functions in tumor biology." (PMID 40510340, 2025). "Mechanistically, ME1-derived NADPH coordinates cancer cell proliferation, invasion, apoptosis resistance, and metabolic adaptation through redox balance maintenance and anabolic pathway activation." (PMID 40906080, 2025). "Although ME1 is overexpressed in various cancers, its role in cancer tumorigenesis and progression remains to be fully elucidated." (PMID 39996805, 2025). "Although this study systematically revealed the relationship between ME1 and various types of cancer, it still has certain limitations." (PMID 40510340, 2025). "Because ME1 is involved in various aspects of cancer and promotes many of its malignant phenotypes, it is expected that ME1 will become a novel drug target in the near future." (PMID 39996805, 2025). "In particular, in low-glucose environments, cancer cells become dependent on ME1 for the supply of NADPH and pyruvate, ME1 has emerged as a novel molecular target for cancer therapy." (PMID 39996805, 2025). "Currently, the molecular mechanism of ME1 has primarily been investigated in specific types of cancer, leaving its role in pan-cancer largely unclear." (PMID 40510340, 2025). "The correlation between ME1 and 14 cancer functional states was assessed using single-cell sequence data from CancerSEA." (PMID 40510340, 2025). "ME1 promotes cancer progression by altering metabolism and stemness, which then increases tumor growth and invasion." (PMID 39996805, 2025). "In this study, we conducted a preliminary analysis of ME1 expression across various cancers, focusing on its expression patterns and fundamental biological characteristics in tumors, particularly in relation to the immune system." (PMID 40510340, 2025). "ME1 is overexpressed in many cancers, contributing to poorer prognosis and more aggressive tumor behavior." (PMID 39996805, 2025).
cancer (continued). "Examples include miR-30a, miR-30c-5p, miR-612, and miR-885-5p, which target ME1 and influence its expression in various cancer contexts." (PMID 39996805, 2025). "All cancers that overexpress ME1 have the potential to benefit from ME1-targeted therapy, making ME1 highly adaptable to cancer." (PMID 39996805, 2025). "These enzymes contribute to anti-apoptotic survival, EMT, and metastasis, further emphasizing the role of ME1 in promoting cancer progression and resistance." (PMID 39996805, 2025). "In OSCC cells, ME1 knockdown increases the NADP/NADPH ratio and decreases the glutathione/glutathione SH (GSH/GSSG) ratio, suggesting that ME1 helps maintain the reducing environment in cancer cells." (PMID 39996805, 2025). "The relationship between ME1 and budding is critical for cancer invasive fronts that exhibit budding." (PMID 39996805, 2025). "Simultaneous upregulation of HIF1α and ME1 is observed at the cancer front, with ME1 expression being induced by hypoxia." (PMID 39996805, 2025). "ME1 promotes the malignancy of various cancers by reprogramming energy metabolism, maintaining redox potential, enhancing stemness, and facilitating EMT." (PMID 39996805, 2025). "This review summarizes the latest research insights into the mechanisms by which ME1 contributes to cancer progression." (PMID 39996805, 2025). "In summary, ME1 is a pivotal functional metabolic enzyme that significantly contributes to the metabolism of both normal and cancer cells." (PMID 40510340, 2025). "Studies have demonstrated that ME1 expression levels influence cancer susceptibility to oxidative phosphorylation (OXPHOS) inhibitors, with elevated ME1 expression diminishing the synthetic lethality between the pentose phosphate pathway (PPP) and OXPHOS." (PMID 40510340, 2025). "ME1 is overexpressed in budding cells at the cancer invasive front, promoting cancer invasion and metastasis." (PMID 39996805, 2025). "A recent study has suggested that malic enzyme 1 (ME1) promotes the Warburg effect in cancer cells and induces EMTs in HNSCC cells." (PMID 36831453, 2023). "Upregulated ME1 in KRASG13D mutant cells is indispensable for cancer development, while miR-30a directly inhibits ME1 expression." (PMID 36755301, 2023). "The major suppliers of NADPH have been reported to be oxPPP, ME1, and 1C metabolism in proliferating and cancer cells." (PMID 35534945, 2022). "Loss of G6PD in cancer cells generates high NADP, induces compensatory increases in malic enzyme 1 and isocitrate dehydrogenase, and inhibits dihydrofolate reductase activity to block folate-mediated biosynthesis." (PMID 34235071, 2021). "We find that PC and ME1 expression in cancer cells are both important for PDAC tumor growth in vivo." (PMID 32648540, 2020). "In a previous study, we reported that overexpression of malic enzyme (ME)-1 in cancer promotes glutaminolysis, resulting in altered energy metabolism, from oxidative phosphorylation to glycolysis." (PMID 32998265, 2020). "ME1 expression in cancer cells also leads to energy metabolism reprogramming from oxidative phosphorylation to glycolysis, resulting in decreased oxygen consumption and increased lactate production, promoting tumorigenicity and tumor growth." (PMID 32998265, 2020). "Tumor budding and ME1 expression were significantly correlated with cancer progression according to both pT and pStage classifications." (PMID 32998265, 2020). "Transplantation of ME1-null cancer cells in vivo also resulted in reduced tumor growth, consistent with published data." (PMID 32648540, 2020). "Although no ME1 inhibitors are currently being evaluated in clinical trials, a strategy combining ME1 and glycolysis inhibition, would provide an effective therapeutic option for cancer treatment." (PMID 31881713, 2019). "Nevertheless, most of what is known about the actions of ME1 in cancer cells is derived from in vitro studies and xenograft transplants to mice." (PMID 30250042, 2018).